ITGAL (integrin subunit alpha L)
Description:
Integrin ITGAL/ITGB2 is a receptor for ICAM1, ICAM2, ICAM3 and ICAM4. Integrin ITGAL/ITGB2 is a receptor for F11R. Integrin ITGAL/ITGB2 is a receptor for the secreted form of ubiquitin-like protein ISG15; the interaction is mediated by ITGAL. Involved in a variety of immune phenomena including leukocyte-endothelial cell interaction, cytotoxic T-cell mediated killing, and antibody dependent killing by granulocytes and monocytes. Contributes to natural killer cell cytotoxicity. Involved in leukocyte adhesion and transmigration of leukocytes including T-cells and neutrophils. Acts as a platform at the immunological synapse to translate TCR engagement and density of the ITGAL ligand ICAM1 into graded adhesion. Required for generation of common lymphoid progenitor cells in bone marrow, indicating a role in lymphopoiesis (By similarity). Integrin ITGAL/ITGB2 in association with ICAM3, contributes to apoptotic neutrophil phagocytosis by macrophages. Integrins ITGAL:ITGB2 functions as a receptor of the neuron-specific adhesion molecule ICAM5 ensuring neuron cell-leukocyte adhesion. Integrin ITGAL/ITGB2 that functions as a signaling receptor of ICAM2, ensuring leukocyte cell-cell adhesion on resting cells.
Synonyms: CD11a; HNA-5; LFA-1; LFA1A; EV6
Tractability: Small molecule: an approved drug acts on it; a structure with a bound ligand is known; a high-quality ligand is known; it has a high-quality binding pocket; it belongs to a druggable protein family. Antibody: an approved drug acts on it; UniProt places it where antibodies can reach, with high confidence; its Gene Ontology location is reachable by antibodies, with high confidence; UniProt predicts a signal peptide or a membrane-spanning region. PROTAC: ubiquitination databases record sites on it; its protein half-life has been measured; a small molecule that binds it is known.
Target class: Adhesion
Chemical probes: BI-1950 (high quality), BMS-688521
Gene: Protein-coding gene on chromosome 16 (30,472,658 to 30,523,567, forward strand). Ensembl gene ENSG00000005844.
Subcellular location: Cell membrane; Membrane raft
Pathways (Reactome):
Immune System: Immunoregulatory interactions between a Lymphoid and a non-Lymphoid cell; Neutrophil degranulation
Extracellular matrix organization: Integrin cell surface interactions
Gene expression (Transcription): RUNX3 Regulates Immune Response and Cell Migration
Hemostasis: Cell surface interactions at the vascular wall
Gene Ontology:
Molecular function: cell adhesion molecule binding; cell adhesion receptor activity; ICAM-3 receptor activity; protein binding; signaling receptor activity; protein-containing complex binding
Biological process: cell adhesion mediated by integrin; cell-cell adhesion mediated by integrin; cell-matrix adhesion; heterophilic cell-cell adhesion; leukocyte cell-cell adhesion; memory T cell extravasation; neuron cell-cell adhesion; receptor clustering; T cell activation via T cell receptor contact with antigen bound to MHC molecule on antigen presenting cell; cell adhesion; cell-cell adhesion; inflammatory response; integrin-mediated signaling pathway; signal transduction; T cell activation
Cellular component: cell surface; extracellular exosome; integrin alphaL-beta2 complex; membrane; membrane raft; plasma membrane; integrin complex; specific granule membrane; cell-cell junction; external side of plasma membrane; immunological synapse; secretory granule membrane
Genetic constraint (gnomAD): Loss-of-function variants: 59 observed, 123.26 expected, observed/expected ratio (o/e) 0.48, 90% interval 0.39 to 0.6. The upper end of that interval is the gene's LOEUF score, 0.6, which puts it in group 2 of 6, group 1 being the genes least tolerant of losing a copy. Missense variants: 1,177 observed, 1,451.3 expected, observed/expected ratio (o/e) 0.81, 90% interval 0.77 to 0.85. Synonymous variants: 536 observed, 581.14 expected, observed/expected ratio (o/e) 0.92, 90% interval 0.86 to 0.99.
Homologues: Orthologues: macaque ITGAL (95% identical), dog ITGAL (79% identical), rabbit ITGAL (78% identical), guinea pig ITGAL (76% identical), pig ITGAL (74% identical), rat Itgal (72% identical), mouse Itgal (70% identical), chimpanzee ITGAL (29% identical), Drosophila melanogaster mew (19% identical), Caenorhabditis elegans pat-2 (18% identical), Caenorhabditis elegans ina-1 (18% identical), Drosophila melanogaster if (18% identical), and 3 more. Paralogues in human: ITGAX (31% identical), ITGAM (31% identical), ITGAD (30% identical), ITGA1 (27% identical), ITGA10 (26% identical), ITGA11 (26% identical), ITGA2 (25% identical), ITGAE (24% identical), ITGA9 (20% identical), ITGA4 (19% identical), ITGA5 (19% identical), ITGA8 (18% identical), and 5 more.
Diseases named in the same sentence as ITGAL in open-access papers:
ITGAL is named in the same sentence as 155 diseases in open-access papers, as found by Europe PMC text mining. Sharing a sentence is not in itself a finding about the gene and the disease. The quoted sentences say what the papers report.
lupus (31 papers, 2006 to 2025). "It was later demonstrated that hypomethylation of the CpG sites within the regulatory sequence of ITGAL was observed in T cells from individuals who were treated with lupus-associated drugs, resulting in over-expression of CD11a." (PMID 28085900, 2017). "Bisulfite sequencing was used to determine the methylation status of the ITGAL promoter and flanking regions in T cells from lupus patients and healthy subjects and in T cells treated with DNA methylation inhibitors." (PMID 38510251, 2024). "Bisulfite sequencing was used to determine the methylation status of the ITGAL promoter and flanking regions in T cells from lupus patients and healthy subjects." (PMID 38510251, 2024). "Patients with active lupus show lower methylated cytosine content (deoxymethylcytosine, about 4%) in their many genes of T-cells, as well as in ITGAL and TNFSF7." (PMID 29803202, 2018). "The upstream ITGAL promoter is demethylated in active lupus patients compared to controls, the degree of demethylation correlating with disease activity." (PMID 27199979, 2016). "Subsequently, hypomethylation of certain genes have been identified as important in lupus T cells, such as ITGAL (CD11a), CD40LG (CD40L), TNFSF7 (CD70), Killer-cell immunoglobulin-like receptor (KIR2DL4), perforin (PRF1), and CD5 in lupus B cells." (PMID 25566322, 2014). "In this work we have determined the transcript expression of five genes that have proved relevant to lupus and we have confirmed previous observations of high expression of three of them: ITGAL, PRF1, and CD70." (PMID 23029299, 2012). "Similarly, our results revealed that in PBMC from SLE patients, several genes including CD70, ITGAL, selectin-l, and IL-13, all of which are hypomethylated and intensify lupus in different ways, are reduced by MSC." (PMID 33282947, 2020). "Moreover, the epigenetic mechanism of lupus suggests that the abnormal DNA hypomethylation of T cells results in the excessive expression of methylation-sensitive autoimmunity-related genes such as CD70, ITGAL, selectin-l, IL-4, and IL-13 in lupus." (PMID 33282947, 2020). "The genes encoding perforin (PRF1), CD11a (ITGAL), CD70 (TNFSF7), CD40L (CD40LG), and the killer cell immunoglobulin-like receptor (KIR) genes are normally suppressed by DNA methylation in CD4+ T cells, but are demethylated and over-expressed by CD4+ T cells from patients with active lupus." (PMID 28239687, 2016). "In addition to type I IFN signature genes, many other hypomethylated genes (such as CD70, ITGAL, IL10, and IL17) have been identified in lupus cells, which contributed to abnormal immune cell activation and inflammation in lupus." (PMID 38153351, 2023). "Hypomethylation in the promoter region of some genes, such as Integrin Subunit Alpha L (ITGAL, Gene ID: 3683), Perforin 1 (PRF1, Gene ID: 5551), and members of Tumor Necrosis Factor Receptor Superfamily (TNFSF5 and TNFSF7, Gene ID: 959 and 970, respectively), were reported in lupus T cells." (PMID 29387007, 2017).
psoriasis (20 papers, 2006 to 2025). An autoimmune condition characterized by red, well-delineated plaques with silvery scales that are usually on the extensor surfaces and scalp. "Moreover, FCGR3A was found to interact with known therapeutic targets of psoriasis such as CD2, Tumor necrosis factor (TNF), Integrin subunit alpha L (ITGAL), and IL17A." (PMID 39883516, 2024).
melanoma (12 papers, 2012 to 2025). A malignant, usually aggressive tumor composed of atypical, neoplastic melanocytes. "Our mIHC analysis of multiple clinical tissue samples further demonstrated the association between ITGAL and melanoma invasion, but the specific mechanisms still require further exploration through animal experiments." (PMID 37388230, 2023). "First, because most of the results are based on online platform databases, which would be discrepant, and second, further experiments are required to validate immune-related molecular mechanisms underlying the function of ITGAL in melanoma, which will be a future study." (PMID 37388230, 2023). "Our analysis revealed that a higher expression of ICAM, ITGAL (LFA-1α), and ITGB2 (LFA-1β) was significantly correlated with a low risk for most cancer types, particularly melanoma." (PMID 40277945, 2025). "TNMplotter database analysis showed that ITGAL gene expression increased sequentially in normal tissue, primary melanoma, and metastatic melanoma, which we further validated using immunohistochemical staining to obtain similar results." (PMID 37388230, 2023). "Subsequently, comparing the normal cells and tissue samples, we validated that ITGAL was highly expressed in melanoma samples using qPCR, WB, and mIHC." (PMID 37388230, 2023). "In this study, we explored the expression levels and clinical features of ITGAL in melanoma by systematically analyzing data from public databases and clinically collected samples." (PMID 37388230, 2023). "Our results show that increased expression of ITGAL is associated not only with PD1 and CTLA4, but also with other potential melanoma checkpoints (LAG-3, Tim-3, and TIGIT)." (PMID 37388230, 2023). "At the same time, we used the TIMER and GEPIA databases to explore the correlation between ITGAL and biomarkers of different tumor-infiltrating lymphocytes (TILs) in melanoma." (PMID 37388230, 2023). "The findings reveal the key role of ITGAL in melanoma and its potential mechanism of regulating tumor immune infiltrating cells, highlighting its potential as a diagnostic biomarker and therapeutic target for advanced melanoma." (PMID 37388230, 2023). "This study investigates the relationship between ITGAL expression and immune infiltration, clinical prognosis, and specific types of T cells in melanoma tissue." (PMID 37388230, 2023). "In this study, we combined various databases and biological experiments to study the relationship between the expression of ITGAL and immune infiltration in melanoma, and performed functional analysis of ITGAL-mediated TCGA-SKCM data." (PMID 37388230, 2023). "Although histological classification or clinical stage can help predict the prognosis of melanoma patients, there is still a need to explore the relationship between ITGAL expression and clinical features." (PMID 37388230, 2023). "According to the expression of ITGAL in different groups, the results revealed that the level of immune cell infiltration increased with the progression of melanoma." (PMID 37388230, 2023). "Further, the results of Western blotting showed that ITGAL was highly expressed in melanoma compared to normal tissue controls." (PMID 37388230, 2023). "Previous study showed that chemotherapy with propranolol and etodolac increased ITGAL expression and improved recurrence-free survival rates in mice undergoing primary melanoma or Lewis lung carcinoma excision." (PMID 34633989, 2021). "This study revealed the key role of ITGAL in melanoma and the mechanism by which ITGAL may regulate tumor immune infiltrating cells." (PMID 37388230, 2023). "We used the GEPIA database to validate the expression of ITGAL in melanoma." (PMID 37388230, 2023). "In this study, the expression of ITGAL was negatively correlated with the purity of melanoma." (PMID 37388230, 2023). "In particular, the results showed that ITGAL was highly expressed in melanoma." (PMID 37388230, 2023).
melanoma (continued). "Therefore, we use the TIMER and TISIDB databases to explore the relationship between the expression of ITGAL and the immune infiltration in melanoma." (PMID 37388230, 2023). "Then the results of qPCR verified that ITGAL was highly expressed in B16 cells of melanoma." (PMID 37388230, 2023). "We used GEPIA to explore the relationship between ITGAL and these hub genes in melanoma." (PMID 37388230, 2023). "Finally, the ability of sIL18 to limit the progression of B16-F10 melanomas established in WT C57BL/6 mice was abolished with the administration of an antibody blocking the ISG15 receptor integrin alpha L (ITGAL, best known as LFA-1α), as well as by the deletion of Isg5 in malignant cells." (PMID 40263267, 2025). "However, the pathogenesis of ITGAL and melanoma is still unclear." (PMID 37388230, 2023). "Thus, our study provides a novel perspective and evidence for understanding the critical function of ITGAL in melanoma, which may be an immune infiltration-related prognostic indicator." (PMID 37388230, 2023). "Patients exhibiting concurrent high infiltration of CD4+ Th1 and CD8+ T cells and elevated ICAM, ITGAL, and ITGB2 expression had the best clinical outcomes out of the patients with melanoma." (PMID 40277945, 2025). "Our results showed that high expression of ITGAL was significantly positively correlated with CD4+ T cells and CD4+ T cells in melanoma." (PMID 37388230, 2023). "In addition, the relationship between the expression of ITGAL and CD4+ CD8+T cells in melanoma tissue sections was studied by multiple immunofluorescence staining." (PMID 37388230, 2023). "Additionally, ITGAL, ITGAX, and IIT possessed effective ICB biomarker potentials towards glioblastoma, melanoma, gastric cancer, and others, with analogous effectiveness compared to well-established ICB biomarkers." (PMID 37835514, 2023).
COVID-19 (9 papers, 2020 to 2026). A disease caused by infection with severe acute respiratory syndrome coronavirus 2. "Integrin alpha-L (ITGAL) is one of the factor involved in trans-endothelial migration of leukocytes associated with COVID-19 pathogenesis." (PMID 34115763, 2021). "(a) UMAP representations of immune cell populations from healthy participants and COVID-19 patients annotated by cell types (left) and differential expressions of counter receptors ITGAL, SELPLG, and CX3CR1, which are known to interact with surface molecules of activated endothelial cells (right)." (PMID 33752798, 2021). "Integrin subunit alpha L (ITGAL), an integrin involved in monocyte migration across endothelium in anti-viral immune response was strongly activated in non-resident macrophages in severe COVID-19." (PMID 36143338, 2022).
Autoimmunity (8 papers, 2013 to 2025). The occurrence of an immune reaction against the organism's own cells or tissues. "It has been reported that the methylation patterns of ITGAL contributed to the development of autoimmunity, aging and cancer." (PMID 34633989, 2021). "Hypomethylation of DNA in CD4+ T cells from SLE patients leads to the overexpression of genes involved in autoimmunity, including ITGAL (CD11a) and CD70, which contribute to the activation of autoreactive T cells and the production of autoantibodies." (PMID 40046056, 2025).
lung adenocarcinoma (7 papers, 2018 to 2024). A carcinoma that arises from the lung and is characterized by the presence of malignant glandular epithelial cells. "Numerous studies have demonstrated the potential of ITGAL as a molecular marker for immunotherapy in various tumors, However, its role in lung adenocarcinoma has seldom been explored." (PMID 38613346, 2024). "In lung adenocarcinomas, patients with higher levels of ITGAL expression had a higher OS rate (HR=0.74, P=6.7e-03) and PFS rate (HR=0.73, P=3.3e-07)." (PMID 38646528, 2024). "Next, we overexpressed ITGAL in human lung adenocarcinoma A549 cells and explored the effect of ITGAL." (PMID 38613346, 2024). "This is the first comprehensive analysis of ITGAL in the prognosis, immune microenvironment, and immunotherapy of lung adenocarcinoma." (PMID 37256932, 2023). "However, the biological functions of ITGAL in lung adenocarcinoma (LUAD) remain poorly understood." (PMID 38613346, 2024). "We conducted a pan‐cancer analysis of ITGAL in tumours through the TIMER database, and the results showed that ITGAL was significantly more highly expressed in normal lung tissues than in the lung adenocarcinoma (LUAD) tissues." (PMID 38613346, 2024).
autoimmune disease (6 papers, 2014 to 2025). A disorder resulting from loss of function or tissue destruction of an organ or multiple organs, arising from humoral or cellular immune responses of the individual to their own tissue constituents. "Currently, anti-ITGAL antibodies, such as efalizumab, have been reported to be well-established in autoimmune diseases." (PMID 36329800, 2022). "Hypermethylation of the ITGAL promoter region has also been observed in CD4+ T cells from other autoimmune diseases." (PMID 25986394, 2015).
gastric cancer (6 papers, 2022 to 2024). A primary or metastatic malignant neoplasm involving the stomach. "A high ITGAL expression was significantly associated with the type of sample, the subgroup, the tumor stage, the lymph node stage, and the low survival rate for gastric cancer." (PMID 38646528, 2024). "Gastric cancer has been found to express ITGAL significantly more than peritumor samples in several studies." (PMID 38646528, 2024). "ITGAL was previously reported to correlate with immune infiltrates in gastric cancer and acute myeloid leukemia." (PMID 37256932, 2023). "ITGAL is also considered a very important prognostic marker in gastric cancer and acute myeloid leukemia." (PMID 37256932, 2023). "In the aspect of tumors, ITGAL is an independent prognostic biomarker of myeloid leukemia and gastric cancer, and its mediation of tumor occurrence and progression is closely related to the regulation of immune function." (PMID 37324016, 2023). "We examined ITGAL expression in relation to several clinical–pathological parameters in patients, including sample type (healthy/primary tumor), tumor stage (stage 1, 2, 3, and 4), lymph node stage (N0 1, 2, and 3), and gastric cancer subgroup by applying UALCAN." (PMID 35399517, 2022). "Correlation of integrin alpha L (ITGAL) mRNA expression and clinical prognosis in gastric cancer with different clinicopathological factors by Kaplan–Meier plotter." (PMID 35399517, 2022). "However, the relation between ITGAL and the prognosis of gastric cancer (GC) and tumor-infiltrating lymphocytes (TILs) are not well understood." (PMID 35399517, 2022).